BCL9 (BCL9 transcription coactivator)
Diseases named in the same sentence as BCL9 in open-access papers (continued):
Sharing a sentence is not in itself a finding about the gene and the disease.
tumor (continued). "In conclusion, this study presents a nanotechnology-enabled strategy to overcome longstanding barriers in peptide drug delivery and demonstrates the feasibility of targeting β-catenin/BCL9 interactions to suppress tumor progression and enhance immunotherapy responsiveness." (PMID 40948801, 2025). "Bcl9@TP displayed robust tumor-suppressive properties when used alone." (PMID 40948801, 2025). "To determine whether Bcl9@TP can effectively suppress Wnt/β-catenin-driven tumor progression and immune evasion, we investigated the therapeutic potential in vivo using an immunocompetent subcutaneous tumor model." (PMID 40948801, 2025). "APC (p = 1.7e-20), BCL9 (p = 0.0006), CREBBP (p = 8.5e−5), FLCN (p = 1.39e−7), NSD2 (p = 0.002), and EP300 (p = 1.42e−6) all had significantly higher mutation rates in MSLN low expressing tumor samples compared to MSLN high expressing tumor samples." (PMID 39174744, 2024). "BCL9, a key transcriptional co-activator of the Wnt pathway and highly expressed in tumors, activates the Wnt/β-catenin signaling pathway by interacting with β-catenin, promoting its nuclear translocation, and promoting tumor progression." (PMID 37351175, 2023). "This phenomenon indicates that high expression of BCL9 may accelerate ACC tumor progression by triggering the Wnt tumorigenic pathway." (PMID 38269250, 2023). "Prior research has shown that BCL9 enhances tumor cell proliferation in vitro." (PMID 38269250, 2023). "Kaplan−Meier survival analysis showed that the survival rates after the second curative resection of patients with BCL9 somatic mutations or amplifications in their recurrent tumor were significantly lower than those of patients without such changes." (PMID 35078970, 2022). "It was found that BCL9 is an essential co-activator in the Wnt/β-catenin signaling pathway, enhances β-catenin-mediated transcription activity, and increases cell proliferation, invasion, migration, and metastatic potential of tumor cell." (PMID 34978646, 2022). "In this way, GdOFBAu could successfully deliver Bcl9 peptides to MC38 tumor-bearing mice to inhibit tumor growth and increase the response of mice against anti-PD1 while exhibiting favorable biosafety and biocompatibility at the same time." (PMID 35745877, 2022). "Moreover, another prior report has suggested that miR-30 can act as a tumor suppressor by modulating the oncogenic Wnt/β-catenin/BCL9 pathway in a broad range of human cancers." (PMID 35368023, 2022). "Additionally, in our EMS mice, Exo carrying AFAP1-AS1 affected EMS also through miR-15a-5p/BCL9, contributing changes of tumor weight and size in EMS mice." (PMID 35513844, 2022). "In vivo HCC mouse models showed that BCL9 knockdown reduced tumor growth and pulmonary metastasis." (PMID 35078970, 2022). "The role of BCL9-driven Wnt signaling in macrophage polarization and how suppression of BCL9 affects tumor immune microenvironment remain unclear." (PMID 34566638, 2021). "To further study how Bcl9 depletion inhibits the delineation from tumor-associated monocytes to NK-like non-functioning cells, we performed pseudotime analysis on the cells from Step 1 re-clustering (clusters 2, 9, and 12)." (PMID 34566638, 2021). "Conditional knockout of both Bcl9 and Bcl9L resulted into tumor cell death." (PMID 34545187, 2021). "This suggests that the Bcl9/Bcl9L-β-catenin interaction is critical for tumor progression." (PMID 34545187, 2021). "The rationale behind this was to mimic the “treatment” of tumor patients by inhibition of BCL9/9L." (PMID 33085215, 2021). "Alterations in the proportions of T-cell subpopulations, including decreased percentages of CD8+ T cells, tumor-associated macrophages, cancer-associated fibroblasts, tumor endothelial cells, tumor-associated neutrophils, and dendritic cells, indicate a complex TIME in tumors regulated by BCL9." (PMID 34417435, 2021).
tumor (continued). "Interestingly, Bcl9-shRNA or hsBCL9CT-24 treated CT26 tumor cells co-cultured with CD8+ T cells promoted the proliferation of CD8+ T cells in vitro." (PMID 34417435, 2021). "Furthermore, miR‐140‐3p expression level and BCL9 or BCL2 mRNA level in tumor tissues were negatively correlated." (PMID 33838016, 2021). "To investigate whether Bcl9 depletion affects tumor immune infiltration, we characterized immune cells derived from CT26 and MC38 tumors implanted in immunocompetent mice by flow cytometry." (PMID 34417435, 2021). "In the current study, we determined the level of BCL9 in normal and tumor tissues of CRC patients." (PMID 33838016, 2021). "MiR‐140‐3p served as a tumor suppressor in CRC via targeting BCL9 and BCL2." (PMID 33838016, 2021). "Taken together, this work supports that miR‐140‐3p exerts as a tumor suppressor in CRC progression via targeting BCL9 and BCL2, and suggests miR‐140‐3p‐BCL9/BCL2 axis may be applied in miRNA‐based therapy and prognostication of CRC." (PMID 33838016, 2021). "BCL9 plays a key role in tumor progression and remodeling of the tumor microenvironment." (PMID 34277614, 2021). "This shows that the effects of BCL9 KD and BCL9 inhibitor treatment on the function and differentiation of endothelial cells/fibroblasts can affect the prognosis of tumor patients, and this may also lay an experimental foundation for clinical medication." (PMID 33552975, 2020). "In other words, the enrichment of BCL9-endo-Score cells in the tumor may mean that the tumor’s angiogenesis is hindered." (PMID 33552975, 2020). "B (top), tumor growth was significantly reduced in mice implanted with BCL9 knockout RKO cells." (PMID 31911584, 2020). "Indeed, intestinal deletion of Bcl9 blocked tumourigenesis in these mice and essentially cured them of their neoplastic disease." (PMID 30760710, 2019). "In addition, BCL9 silencing decreased the migration of tumor cells and suppressed expression of vascular endothelial growth factor (VEGF)." (PMID 30770859, 2019). "In addition, we uncovered evidence for increased tumour retention in Bcl9-deleted ApcMin intestines, but this undesirable effect was not evident in the Apc1322T model." (PMID 30760710, 2019). "Therefore, this undesirable effect of Bcl9 deletion on tumour retention in the ApcMin model partially negates the beneficial effects of Bcl9 loss in curbing β-catenin-dependent neoplastic gene expression." (PMID 30760710, 2019). "This, together with the scaffolding role of Bcl9, readily explains why the transcriptional profile of the QKO tumours is largely determined by Bcl9 loss and, by implication, why the latter has such a profound impact on β-catenin-dependent intestinal neoplasia in both Apc models." (PMID 30760710, 2019). "Furthermore, murine xenograft models transplanted with the HMCL MM1.s in which BCL9 was knocked down by shRNA, showed reduced tumor burden, decreased metastasis, and prolonged survival compared to shRNA control mice." (PMID 29776381, 2018). "The tumor volume and weight were obviously decreased in BCL9-p-ko and BCL9-ko groups." (PMID 28074862, 2017). "However, given existing evidence, BCL9 inhibition may represent a promising therapeutic strategy to enhance tumor sensitivity to anti-PD-1 treatment." (PMID 40362354, 2025). "Notably, combining Bcl9@TP with anti-PD-1 therapy led to a more pronounced suppression of proliferative activity, with an approximate 70% reduction in Ki-67 positivity, consistent with the observed tumor growth inhibition." (PMID 40948801, 2025). "This reduction may be attributed to the interference of CA with β‐catenin/BCL9 interactions, leading to a diminished infiltration of immunosuppressive T cells into the tumor and consequently enhancing the responsiveness of ABCA‐treated tumors to Anti‐PD1 therapy." (PMID 39431325, 2024).
tumor (continued). "In contrast, disrupting the interaction of Bcl9/Bcl9L with β-catenin, either by deletion of their HD2 domains or by a point mutation in the N-terminal domain of β-catenin (D164A), diminished primary tumor growth and tumor cell proliferation and reduced tumor cell invasion and lung metastasis." (PMID 34545187, 2021). "Immunohistochemical staining also revealed that Bcl9 and Bcl9L proteins were both still expressed in cytosols and nuclei of tumor cells of MCre+ genotype, suggesting either a low recombination efficiency or a competitive selection against recombined tumor cells." (PMID 34545187, 2021). "We then examined whether Bcl9 depletion has a synergistic effect with anti-PD-1 on tumor growth." (PMID 34417435, 2021). "Therefore, this work provides additional insights into the role of BCL9 in tumor progression, and points towards new avenues for therapeutic intervention by targeting BCL9 itself or blockade of neurotransmitter receptors or calcium channels with FDA approved drugs." (PMID 31911584, 2020). "Importantly, these tumours were escapers that retained expression of both Bcl9 and Bcl9l." (PMID 30760720, 2019). "Moreover, deletion of Bcl9/9l resulted in a profound alteration in tumour distribution." (PMID 30760720, 2019). "Whether there are gene mutations in the Wnt/β-catenin pathway or not, BCL9 can enhance the gene transcriptional activity mediated by β-catenin, thereby promoting tumor proliferation, migration and invasion." (PMID 28769030, 2017). "BCL9 possesses a potent transcription activation domain and might function as an oncogene by providing an alternative pathway for β-catenin activation and subsequent tumor progression." (PMID 26384318, 2015). "In contrast, a few genes (TDGF1, GHRH, and BCL9) reported to be involved in promoting cell proliferation are downregulated which highlights the fact that cellular transformation is a multistage process with a sustained tug of war between tumor suppressor and tumor promoter." (PMID 23216862, 2012). "Across tumor cell populations, TBX3 expression significantly overlapped with that of BCL9 and BCL9L in individual cells." (PMID 40343989, 2025). "To investigate the immunomodulatory effects of Bcl9@TP on the TME, we performed immunofluorescence staining on tumor tissues from each treatment group." (PMID 40948801, 2025). "By analyzing LC-MS/MS data from the CPTAC cohort, we found that both BCL9 and TPX2 levels were significantly elevated in ccRCC tumor samples compared to paired normal adjacent tissues." (PMID 40362354, 2025). "BCL9 and TPX2 are significantly upregulated proteins in tumor tissues compared to the normal adjacent tissues (NATs)." (PMID 40362354, 2025). "Here, we show that targeting BCL9/BCL9L enhanced antigen presentation by stimulating cDC1 activation and infiltration into tumor." (PMID 38811552, 2024). "In summary, BCL9 inhibition promotes CD8+ T cell proliferation and IFN-γ secretion as well as cross-presentation in MC38-OVA tumor-bearing models." (PMID 38811552, 2024). "Having established that targeting BCL9/BCL9L facilitates cDC1 activation and tumor infiltration, we next examined how cDC1 contribute to CD8+ T cell responses in tumors after the inhibition of BCL9." (PMID 38811552, 2024). "Our studies showed that targeting BCL9/BCL9L facilitates antigen presentation and tumor infiltration of cDC1, as well as boosts tumor infiltration of CD8+ T cells, indicating a critical role of targeting BCL9/BCL9L in overcoming immunotherapy resistance." (PMID 38811552, 2024). "We demonstrated that targeting BCL9/BCL9L facilitates the antigen presentation and tumor infiltration of cDC1, as well as boosts the tumor infiltration of CD8+ T cells, thereby improving the responses to cancer immunotherapy." (PMID 38811552, 2024).
tumor (continued). "CM-CA developed in this work is intended to employ CA as an active component for intracellular modulation of β-catenin/BCL9 PPI, with the anticipation of mitigating the systemic toxicity of CA by enhancing its tumor-targeting capability." (PMID 37881428, 2023). "In agreement with the in vitro studies, analysis of an in vivo HCC mouse model showed that the WT or mutant BCL9, especially BCL9D349V and BCL9S278N, substantially promoted tumor growth and pulmonary metastasis." (PMID 35078970, 2022). "In addition, we identified recurrence-specific mutations and copy-number gains in BCL9, leading to WNT/β-catenin signaling activation and an immune-excluded tumor microenvironment, which suggests that BCL9 might serve as a new therapeutic target for recurrent HCC." (PMID 35078970, 2022). "MiR-30c acts as a tumor suppressor, and it inhibits TGF-β-induced Serpine 1 and/or B-Cell CLL/Lymphoma 9 Protein (BCL9) to suppresses cell growth." (PMID 36016398, 2022). "Pharmacological inhibition of Bcl9 in mice and genetic knockdown of Bcl9 with shRNA in CT26 tumor cells was performed." (PMID 34026600, 2021). "The mRNA levels of BCL9 and BCL2 were found to be upregulated in the tumor tissues compared with adjacent normal tissues." (PMID 33838016, 2021). "As a tumor-suppressor miRNA, miR-30c suppresses cell growth by inhibiting TGF-beta-induced Serpine 1 and/or B-Cell CLL/Lymphoma 9 Protein (BCL9)." (PMID 34069740, 2021). "In Bcl9-depleted MC38 tumors, cytotoxic CD8+ T cells were also significantly increased, while the ratio of tumor-infiltrated Treg cells were decreased." (PMID 34417435, 2021). "By enhancing communication among tumor cells and cells from the TME, BCL9 promotes tumor progression by increasing tumor growth, tissue remodeling, and infiltration by stromal cells." (PMID 31911584, 2020). "Although no major histomorphologic differences were observed between engrafted wild-type and BCL9 knockout RKO cells, the tumor cell component in RKO wild-type engrafted tumors was more heterogeneous than in RKO BCL9 knockout engrafted tumors (bottom)." (PMID 31911584, 2020). "In order to further study the clinical significance of BCL9-endo-Score, we performed Louvain algorithm cluster analysis and UMAP reduction of dimensions for all TCGA tumor patients based on their mRNA expression similarity." (PMID 33552975, 2020). "A gene down-regulated in miR-30c-1* (FC = 0.59) and in miR-193b (FC = 0.74) transfected cells was B-cell CLL/lymphoma 9 protein (BCL9), known to enhance invasion and to promote tumor progression." (PMID 30197759, 2018). "To further evaluate the role of BCL9 in the progression of human HCC, we established a xenograft tumor model." (PMID 28074862, 2017). "Mechanistic studies confirmed that Bcl9@TP competitively disrupts β-catenin/BCL9 interactions, destabilizes the β-catenin/TCF transcriptional complex, and inhibits aberrant Wnt signaling activation, thereby suppressing tumor growth." (PMID 40948801, 2025). "In summary, our data uncover that targeting BCL9/BCL9L plays a key role in cDC1-regulated presentation of tumor-derived antigens and subsequently in cDC1-triggered activation and tumor infiltration of CD8+ T cells, constituting a positive feedback loop required for optimal antitumor immunity." (PMID 38811552, 2024). "Specifically, we hypothesized that by inhibiting BCL9 activity, we could shift the balance of CD226 and CD96 checkpoints towards more cytotoxicity and thereby impede tumor growth." (PMID 34417435, 2021). "BCL9 (B cell CLL/lymphoma 9), a component of Wnt/β‐catenin pathway, can form a complex with β‐catenin and activate Wnt/β‐catenin targeted‐genes to promote tumor development." (PMID 33838016, 2021). "Therefore, studies in NOD/SCID mice transplanted with MM1S BCL9 shRNA cells showed an increased in OS, fewer GFP tumor nodules, and smaller foci of cells infiltrating the bone marrow." (PMID 34205916, 2021).
tumor (continued). "In addition, BCL9 and BCL2 protein levels were increased in tumor tissues compared with adjacent normal tissues." (PMID 33838016, 2021). "Furthermore, we provided evidence for miR‐140‐3p as a tumor suppressor in CRC progression, regulated cell proliferation, migration, invasion, and apoptosis via targeting BCL9 and BCL2." (PMID 33838016, 2021). "Motivated by this and the knowledge of a functional requirement of Bcl9 and Bcl9L for EMT in MMVT-PyMT-derived tumor cell lines in vitro, we next studied the expression of both proteins during the different stages of tumor progression in mammary glands of MMTV-PyMT transgenic mice in vivo." (PMID 34545187, 2021). "It was found that in CD8+ T cell-depleted tumor-bearing mice anti-PD-1 no longer exerted an additional inhibitory effect on tumor growth when combined with Bcl9 depletion." (PMID 34417435, 2021). "To confirm whether miR‐140‐3p overexpression regulates the expression of BCL9 and BCL2, we performed real‐time PCR on xenograft tumor tissues." (PMID 33838016, 2021). "In Bcl9-depleted MC38 tumors, CD226+CD8+ T cell tumor infiltration was also increased." (PMID 34417435, 2021). "In summary, we found that BCL9 promotes neural features through its interaction with paraspeckle proteins in a specific subtype of CRC, and enhances tumor progression by promoting neurotransmitter-dependent communication between tumor cells and cells of the TME." (PMID 31911584, 2020). "Calcium transients were synchronous among individual tumor cells and independent of direct physical contact, but lack of BCL9 reduced this synchronicity, as well as their amplitude and frequency." (PMID 31911584, 2020). "BCL9 knockdown enhanced the survival of the xenograft mouse model of CRC and attenuated the expression of pro-angiogenic factors (e.g., CD44, and VEGF), which resulted in a reduction of tumor metastasis and angiogenesis." (PMID 33276489, 2020). "If a small molecule can destroy the interaction interface of proteins, such as β-catenin–BCL9–TCF, to prevent them from forming a complex, then this may inhibit the Wnt signaling pathway in tumor cells and prevent the occurrence and development of tumors." (PMID 31827404, 2019). "Deletion of Bcl9/9l significantly extended survival and at endpoint, these mice had developed tumours as opposed to displaying the crypt-progenitor phenotype like the control cohort." (PMID 30760720, 2019). "Our RNA profiling data suggested that Bcl9 loss contributed rather more than Pygo loss to the QKO-dependent trend reversals, perhaps explaining why the tumour phenotypes of the QKO mice resembled those of Bcl9/B9l rather than Pygo1/2 DKO." (PMID 30760710, 2019). "To directly assess the role of T cells in reducing tumor growth in Bcl9-shRNA tumors during anti-PD-1 treatment, we depleted CD8+ T cells using a CD8-neutralizing antibody and subsequently examined the effect of Bcl9-shRNA combined with anti-PD-1 on tumor growth." (PMID 34417435, 2021). "To further validate whether there was a selection against tumor cells lacking both Bcl9 and Bcl9L, we examined whether the genetic deletion of Bcl9/Bcl9L affected tumor cell survival." (PMID 34545187, 2021). "Therefore, miR‐140‐3p suppressed tumor growth and metastasis in CRC by directly targeting BCL9." (PMID 33838016, 2021). "BCL9 expression was also not induced in our tumor models, similar to our previous studies." (PMID 27811361, 2016). "Interestingly, subcutaneous grafting of the same organoids in immuno-compromised mice resulted in tumor regression in allografts lacking Bcl9/9l while the wild-type organoids grew exponentially, consistent with their Apc −/− and mutated Kras background." (PMID 26844253, 2015).
tumor (continued). "Interestingly, a search for human homologs allowed the characterization of a BCL9/9L-KO signature of 378 genes that was then used to probe public human CRC databases revealing that hazards of relapse and death are both significantly reduced in patients displaying BCL9/9L-KO-like tumor profiles." (PMID 26844253, 2015). "Hence, increased expression of both BCL9 and CHD1L may have tumor promoting effects." (PMID 23825644, 2013).